TNFSF10 (TNF superfamily member 10)
Diseases named in the same sentence as TNFSF10 in open-access papers (continued):
Sharing a sentence is not in itself a finding about the gene and the disease.
tumor (2,194 papers, 2002 to 2026). "In contrast, the TNFSF10 gene encodes TNF-related apoptosis-inducing ligand (TRAIL), which promotes antitumor activity by inducing tumor cell apoptosis." (PMID 41429574, 2026). "Their TME appears to balance pro-apoptotic signals (e.g., high expression of TNFSF10, which encodes TRAIL) with tumor-cell survival pathways, a duality observed in other malignancies." (PMID 41155518, 2025). "Pro-inflammatory (TNFSF10+) and pro-tumor (SPP1+) subtypes were linked to distinct TME profiles, immunotherapy responses, and clinical outcomes." (PMID 40422244, 2025). "TNFSF10 is the gene that encodes TRAIL, a protein that induces apoptosis in tumor cells, which differed in expression levels by European Leukemia Net risk group in AML patients." (PMID 34727888, 2021). "TNFSF10 encodes for a cytokine in the tumor necrosis factor family that mediates cell apoptosis in response to tumor cells and infection." (PMID 34484194, 2021). "TNFSF10, also known as TRAIL, is a death receptor ligand known to induce apoptosis in transformed and tumor cells; TFNSF10 was up-regulated in PRR15-deficient cells (8.1-fold, p = 0.011)." (PMID 28380025, 2017). "Tnfsf10 encodes TRAIL, a cytokine involved in induction of apoptosis in transformed and tumor cells." (PMID 27736906, 2016). "Gene ablation studies have revealed that tumor necrosis factor-related apoptosis-inducing ligand (TRAIL, Apo2L, TNFSF10) plays a crucial role in tumor surveillance, as TRAIL-deficient mice exhibit an increased sensitivity to different types of tumorigenesis." (PMID 21463519, 2011). "TNFSF10 (tumor necrosis factor (ligand) superfamily, member 10, TRAIL), a gene associated with apoptosis in transformed and tumor cells and recently shown to have direct anti-viral activity against dengue virus, is induced early but only transiently." (PMID 18986530, 2008). "Additionally, TNFSF10 (encoding TRAIL) binds to its receptor TNFRSF10B (DR5) to induce apoptosis in tumor cells." (PMID 40891683, 2025). "Our analysis revealed that CCL22 was expressed at low levels across all cell types, whereas TNFSF10 exhibited higher expression in cancer cells compared with other cell types in the tumor microenvironment." (PMID 41295982, 2026). "In TCGA-BRCA and TCGA-PRAD patient datasets, both CCL22 and TNFSF10 expression were positively correlated with tumor infiltration of some immune cell types." (PMID 41295982, 2026). "The transcriptional biomarker score we developed is based on the expression of two immune-related genes, CCL22 and TNFSF10, each playing distinct roles in immune regulation and tumor biology." (PMID 41295982, 2026). "Conversely, some genes, including CXCR4, KITLG, STAT3, and TNFSF10, were downregulated, suggesting a potential suppression of specific pathways related to tumor proliferation and vascular development." (PMID 39861616, 2025). "TNFSF10 is a tumor necrosis factor ligand super family member that can activate apoptosis in many tumor cell lines." (PMID 40454173, 2025). "Regarding cytotoxicity-related genes, GZMB and SYTL3 were up-regulated in the NK1 cluster, while PFR1 (perforin) and TNFSF10 (TRAIL) were down-regulated in tumor-infiltrating iNK cells as compared to preinfusion iNK cells." (PMID 40315330, 2025). "In the immune monitoring of tumor cells, TNFSF10 can also function to control inflammation by inducing apoptosis of macrophages and neutrophils." (PMID 38375157, 2024). "The TNFSF10 pathway constitutes an important component of the innate host anti-tumor immune surveillance mechanism, engaging in the selective activation of extrinsic cell death pathways in cancer cells." (PMID 38957470, 2024). "Herein, we found that regulating the level of EIF4G1 can affect the sensitivity of tumor cells to TNFSF10 by altering the expression of TNFSF10 receptors, which has good clinical prospects." (PMID 38405671, 2024).
tumor (continued). "While Fcgr1 and Fcgr4 rely on antibody binding for their tumoricidal activity, tumor necrosis factor-related apoptosis-inducing ligand Tnfsf10, also known as Trail, can directly induce apoptosis selectively in tumor cells." (PMID 39056192, 2024). "Cell death induced by tumor necrosis factor-related apoptosis-inducing ligand (TRAIL, Tnfsf10) has been shown to contribute to anti-tumor effects in epithelial cells including BLCA cells." (PMID 39559365, 2024). "It has been proposed that nanotechnology can be used to induce autophagy in tumor cells by targeting TNFSF10 for tumor treatment." (PMID 37670976, 2023). "The best‐described role for FOXO factors in cancer is to serve as tumor suppressors that induce genes such as TRAIL (TNFSF10) to promote apoptosis and p27 (CDKN1B) to halt the cell cycle." (PMID 36602390, 2023). "In detail, non-metastasis p-EMT tumor cells received more apoptosis signaling from eCAFs/myCAFs ligands while metastasis from eCAFs/myCAFs received more apoptosis signaling from p-EMT tumor cells via TNFSF10." (PMID 35742914, 2022). "We also found that LAIT upregulated the expression of tumour killing molecules Prf1, Gzmb, Ifng, Tnf, and Tnfsf10 (TRAIL) in exhausted and effector memory CD8+ and CD4+ T cells." (PMID 35808806, 2022). "RELT and TNFSF10 had high expression levels in tumor tissues compared with normal tissues, while EDA2R and TNFSF18 had low expression levels in tumor tissues compared with normal tissues in TCGA dataset." (PMID 34484286, 2021). "TNFSF10 was broadly expressed across human normal tissues and was upregulated in tumor tissues according to the comparison results in the present study." (PMID 33850477, 2021). "IFI27 (interferon alpha‐inducible protein 27) is involved in tumor apoptosis signaling pathways, including type‐I interferon‐induced apoptosis and TNFSF10‐induced apoptosis, and regulates the innate immune response." (PMID 33955587, 2021). "The expression of CDH2, MDM2 and TNFSF10 was significantly upregulated in tumor tissue, while expression of PAX8 and FERMT2 was significantly downregulated." (PMID 33850477, 2021). "Follicular epithelial cells in tumor samples from PTC patients with concurrent HT exclusively contained the antitumor interacting pair TNFRSF10A_TNFSF10." (PMID 34805166, 2021). "TRAIL (TNFSF10) is one more ligand of pro-apoptotic receptors that can efficiently lyse the tumor cells." (PMID 34834534, 2021). "We found that CXCL14, TGFβ1, and TNFSF10 were highly expressed in tumor tissues compared with adjacent normal samples." (PMID 34167551, 2021). "It is noteworthy that tumor necrosis binding pathway was dysregulated with differentially expressed genes Tnfsf13, Erap1, Tnfsf10, and Nucb2 (p < 0.05)." (PMID 31888290, 2019). "By contrast, TRAIL (TNFSF10) was unexpectedly down-regulated at day 7, which implied that the tumor cytotoxicity of CIK cells was independent on TRAIL." (PMID 30333226, 2018). "Another TNF superfamily member found to be synthesized selectively by gTAM is TRAIL (TNFSF10), which is known to have direct suppressive effects on tumor cells by inducing cell death." (PMID 29141914, 2018). "Two-way ANOVA showed a significant influence of MADB106 tumor cell intervention and an interaction with diet on relative mRNA concentrations of TNFSF10/TRAIL in spleens of animals." (PMID 28690853, 2017). "After BCL11B inhibition, TNFSF10 was activated at the transcriptional and translational level in tumor T-cell lines such as Jurkat and huT7837." (PMID 28652615, 2017). "In contrast to our results of the primary BRCAs, we found TNFSF-10 to be remarkably upregulated in tumor and stem cells in co-cultures of ADSCs with SK-BR-3 and MCF-7." (PMID 28545495, 2017). "Inhibition of PTGS2 or EGFR signaling is known to sensitize tumor cells to TNFSF10-mediated apoptosis." (PMID 28686677, 2017). "It is possible that colonic MDR1A KO B cells represent the cellular source of enhanced cytotoxic TNFSF10 in the inflamed tumor microenvironment." (PMID 28686677, 2017).
tumor (continued). "The results indicated that let-7c was a key miRNA which regulated 3 tumor toxic molecules including Fas ligand (FasL), TNFSF10 (Trail) and OSM (Oncostatin M)." (PMID 25826780, 2015). "Consistently, we have found 3 tumor suppressive genes which were significantly up-regulated in CIKIL-2 including tumor necrosis factor ligand superfamily member 10 (TNFSF10), CD40 ligand (CD40LG) and interferon regulatory factor 7 (IRF7)." (PMID 25108500, 2014). "Recognized tumor genes, such as EVI1 and MDS1, and genes associated previously with CC (TERC, TNFSF10, and PIK3CA) are located in this region." (PMID 22412903, 2012). "TNFSF10 has been studied extensively in relation to human cancer because of its cytotoxic effects on tumor cells." (PMID 21711548, 2011). "While TNFα or TNFR1,2/TNFRSF1A,1B targeting induce tumor development resistance, TRAIL/TNFSF10 deficiency accelerates hematological malignancies." (PMID 19759901, 2009). "Therefore, TRAIL/TNFSF10 is considered a promising anticancer target for selectively inducing extrinsic apoptosis in tumor cells." (PMID 40230861, 2025). "In the model, ITGA3 and TNFSF10 were identified as risk factors, with high expression adversely affecting the prognosis of PC patients, while CDK11A and RHOG were protective factors, with high expression being favorable for tumor prognosis." (PMID 38956290, 2024). "Based on our data, we speculate that TNFSF10 may not only regulate the autophagy, but also activate the expression of immune-related genes and participate in anti-tumor immune regulation." (PMID 37670976, 2023). "TNFSF10-induced autophagy was found to be cytoprotective by inhibiting MAPK8 which could improve the sensitivity of tumor cells to targeted drugs." (PMID 36959587, 2023). "The results showed that TNFSF10 expression levels were lower in metastasis tumor than primary." (PMID 37670976, 2023). "Then we injected the stable cell lines containing m3E sgRNAs for CBX8, CCND1, PTP4A3, RPS6KA5 and TNFSF10 into nude mice and checked whether tumor growth was repressed." (PMID 38012744, 2023). "NK cells lyse tumour cells via granzyme and TNFSF10 and FASLG, secrete cytokines, primarily Th‐1 type cytokines such as IFNG, TNF and granulocyte/ monocyte colony‐stimulating factor (CSF2) which facilitate the activation of T cells and other innate immune mediators." (PMID 35445563, 2022). "Therefore, we initially assessed TRAIL expression in multiple cell populations isolated from the TME of B16 tumor–bearing mice, and we found substantial upregulation of Tnfsf10 transcript in the TIL compared with the NDLN." (PMID 33483333, 2021). "Lastly, the pro-apoptotic protein TNF-related apoptosis inducing ligand (TRAIL) which is encoded by the gene TNFSF10 was significantly reduced in 468-ΔTC compared to control (p < 0.01), consistent with the decreased tumor latency and increased tumor size observed in the in vivo studies." (PMID 21247495, 2011). "It suggested that TNFSF10 may exert a vital effect on the anti-tumor immune process of SKCM." (PMID 37670976, 2023). "For instance, the tumor necrosis factor ligand superfamily member 10 (TNFSF10), also known as TRAIL, encodes a cytokine that belongs to the tumor necrosis factor (TNF) ligand family, it preferentially induces apoptosis in transformed and tumor cells and was proposed as a prognostic indicator of PC." (PMID 37035749, 2023). "These included key genes associated with cytotoxic anti-tumor T cell responses (GZMA, GZMB, PRF1), co-stimulation of T cells (CD27, CD28, ICOS), and genes associated with other immune processes, including Type I IFN response (TNF, TNFSF10), as well as T cell exhaustion (CTLA4)." (PMID 36698398, 2022). "Interestingly, TNFSF10 also induces a selective apoptosis in a variety of transformed and tumor cells, but not in most normal cells, so much so, that several clinical trials are testing its use against different types of tumor." (PMID 32231163, 2020).
tumor (continued). "Interestingly, the gene encoding for tumor necrosis factor (ligand) superfamily member 10 (TNFSF10), a protein that induces apoptosis in transformed and tumor cells, was found to be downregulated in the 4 cell lines, even though the gene was recurrently gained (MRR 3-13)." (PMID 22412903, 2012). "Silencing TNFSF10 inhibited the proliferation, migration, and invasion of TGCT cells, highlighting its role in tumor progression." (PMID 42131333, 2026). "Meanwhile, TNFSF10‐TNFRSF10B (TRAIL‐DR5) interaction activates the extrinsic apoptotic cascade, triggering caspase‐mediated signaling that culminates in tumor cell apoptosis." (PMID 40891683, 2025). "A decisive tumor‐suppressive role of FoxOs is present upon cellular damage, which results in FoxO‐mediated induction of pro‐apoptotic genes such as TNFSF10 (TRAIL), FASLG (FasL), BCL2L11 (BIM), or BBC3 (PUMA)." (PMID 39533662, 2025). "Further investigation revealed that TNFSF10 [TNF-related apoptosis-inducing ligand (TRAIL)], a key activator of tumor apoptosis, is significantly overexpressed." (PMID 40353763, 2025). "TNFSF10 is a member of the TNF family of tumor necrosis factors and has the function of promoting tumor cell necrosis." (PMID 38405671, 2024). "While tumor infiltrating monocytes exhibited higher CSF1/M-CSF activity compared to peritumoral monocytes, they had lower TRAIL/TNFSF10 expression." (PMID 37404757, 2023). "Major initiators of tumor inflammation such as CCL2, CXCL1, CXCL2, CXCL11, CSF1, LTB, and TNFSF10 were found to increase in both cell lines, while inflammation suppressors like IL13and IL1RN were decreased." (PMID 36831395, 2023). "TNFSF10, either acting as one member of TNF-α family or a death receptor ligand, was discovered to have the capacity of selectively killing tumor cells." (PMID 37670976, 2023). "Tumor-derived exosomes typically contain tumor antigens as well as immunosuppressive proteins such as FasL (Fas ligand)/CD95L, TRAIL (TNF-related apoptosis-inducing ligand)/TNFSF10, and TGF-ß (transforming growth factor ß)." (PMID 37456253, 2023). "In complete agreement with our epigenetic profiling data, gene expression of FAS, FASLG, TNFSF10, TRAF1 and TRAF2 was higher in the clusters corresponding to dysfunctional tumor-infiltrating CD8+ T cells." (PMID 35668194, 2022). "The FOXO protein regulates the expression of genes important for tumor cell growth, such as p27, CDKN1B, TNFSF10, and GADD45." (PMID 36106139, 2022). "The five TNFSF ligand transcripts were differentially expressed by all these subsets, with tumor-infiltrating germinal cells expressing the highest levels of TNF, LTA, TNFSF10 and LTB, and tumor-infiltrating plasma cells expressing the highest levels of FASLG." (PMID 35392082, 2022). "The considerable CXCL1-induced up-regulation of TLR4, TNFSF10/TRAIL, and KITLG expression along with MICA/MHCI down-regulation, enable tumor evasion from immune surveillance." (PMID 34195201, 2021). "During early tumor development, OPG works by interacting with TNF-Related Apoptosis-Inducing Ligand (TRAIL; TNFSF10), another cytokine that is known to promptly induce apoptosis in cell lines." (PMID 34066014, 2021). "From TCGA datasets, FADD, BIRC2/3, TNFSF10, and TNFRSF10B/C/D were overexpressed in tumor cases compared to normal." (PMID 33737574, 2021). "Conversely, levels of the cytotoxic molecule TNFSF10 (TNF-related apoptosis-inducing ligand TRAIL) were decreased compared to blood cells, potentially marking decreased anti-tumor activity." (PMID 33968070, 2021). "TNF superfamily member 10 (TNFSF10), also known as TRAIL, induces the signal transduction of apoptosis in tumor cells." (PMID 33240261, 2020). "In contrast, tumor suppressive mediators made up most inversely correlated genes, e.g. CXCL10, CXCL11, IL15, TNFSF10/TRAIL, and TNFSF14/LIGHT." (PMID 29141914, 2018).
tumor (continued). "Among those putative target candidates, five potential tumor suppressors, including CCNG2, FOXP1, NRG1, LRIG1, and TNFSF10, were shown to have a direct binding site with miR-130b-5p." (PMID 25888956, 2015). "Except for OSM, the expression of all anti-tumor genes including TNF-α, PRF1, GZMB, FasL, TNFSF10 and CD40LG were significantly upregulated in CIK cells compared to PBMC, which were negatively correlated with expression profiles of their potential regulators." (PMID 25826780, 2015). "TNFSF10 (also known as TNF-related apoptosis inducing ligand or TRAIL) is part of the tumour necrosis factor super-family, and contributes to innate anti-tumour immunosurveillance." (PMID 25496077, 2014). "TNFSF10 encodes the cytokine tumor necrosis factor-related apoptosis-inducing ligand (TRAIL) that binds to TNF and induces apoptosis, primarily in tumor cells." (PMID 21711548, 2011). "Tumor necrosis factor-related apoptosis-inducing ligand (TRAIL, Apo2L, TNFSF10), a type II trans-membrane death ligand, has the unique property of inducing apoptosis in tumor cells while sparing normal ones." (PMID 21463519, 2011). "TRAIL/TNFSF10 is a member of the tumor necrosis factor (TNF) death ligand family that selectively initiates extrinsic apoptosis in caspase-8-dependent tumor cells without affecting normal cells." (PMID 40230861, 2025). "Furthermore, PUS10 translocates to the mitochondria during TNF superfamily member 10 (TRAIL)‐induced apoptosis, forming a caspase‐3 amplification loop that disrupts apoptosis and promotes tumour progression." (PMID 39834094, 2025). "Altered molecular targets, such as E-cadherin (CDH1), MMP9, Survivin (BIRC5), Cytokeratin 5 (KRT5), VEGFA, IL15, TNF-α (TNF), TRAIL (TNFSF10), and Tenascin-C (TNC), exhibited increased expression in our study, which correlates with their upregulation in tumor samples from individuals with OC." (PMID 40072102, 2025). "TNFSF10, a small molecule drug that selectively induces apoptosis, is not as hepatotoxic as traditional chemotherapeutic agents; however, some tumor cells are not sensitive to TNFSF10." (PMID 38405671, 2024). "In order to further explore the clinical value of TNFSF10 in anti-tumor immunity, we used the TIDE algorithm for predictive analysis, and we found that the expression of TNFSF10 was higher in patients who could benefit from SKCM immunotherapy." (PMID 37670976, 2023). "We observed significantly increased gene scores for FAS, FASLG and TNFSF10 in C11_CD8 compared with the nondysfunctional/effector tumor-infiltrating CD8+ T cells and earlier dysfunction fates." (PMID 35668194, 2022). "We generated mice with a Treg-restricted Tnfsf10 deletion and surprisingly found no impact on tumor growth in C57BL/6 and BALB/c tumor models." (PMID 33483333, 2021). "We conclude that Treg-restricted deletion of Tnfsf10 does not affect Treg suppression, tumor growth, cell death, or proliferation and function of T cells." (PMID 33483333, 2021). "Our qRT‐PCR results revealed that the expression levels of TNFSF10 (p < 0.01), ECM1 (p < 0.01), and RNF213 (p < 0.01) were significantly increased in advanced LUAD tumor cells, whereas the expression of SCGB3A2 (p < 0.01), SCGB3A1 (p < 0.01), and SFTPC (p < 0.01) was increased in early LUAD." (PMID 33783985, 2021). "Apoptosis-related DEGs, including CASP8 and TNFSF10, were overexpressed in OC3 tumor cells, which might explain the tumor growth retardation of OC3 xenografts." (PMID 32605311, 2020). "In the primary tumor, OPG may interact with another TNF superfamily member, TNF-Related Apoptosis Inducing Ligand (TRAIL; TNFSF10) to prevent apoptosis induction." (PMID 32318347, 2020). "Therefore, both TNFSF10, consistently upregulated and TNFRSF10D, consistently downregulated in the scaffold network, play a dual role of tumor suppressors and promoters." (PMID 33287223, 2020).